SP1 (Sp1 transcription factor)
Diseases named in the same sentence as SP1 in open-access papers (continued):
Sharing a sentence is not in itself a finding about the gene and the disease.
cancer (continued). "C-MYC may be regulated independently of SP1 by several anti-cancer drugs." (PMID 27105533, 2016). "Moreover, since Sp1 regulates expression of both pro-oncogenic and tumor suppressor-like genes, it has been suggested that “a more complete understanding of the function of Sp1 in cancer is required to validate its potential as a therapeutic target”." (PMID 26967243, 2016). "Both SENP3 and Sp1 may over-accumulate in certain types of human cancers." (PMID 26511642, 2016). "Moreover, both ETS and SP1 are reported to promote the transcriptional activity of MTA2, which belongs to metastasis associated family and is highly expressed in tumors, resulting in promotion of cancer cell aggressiveness." (PMID 26177288, 2015). "However, it is unclear whether this mechanism is applicable to the promoter region of the human SP1 gene in cancer cells." (PMID 26703734, 2015). "SP-1 is a ubiquitously expressed transcription factor, which belongs to the C2H2-type zinc-finger protein family, and is found to be associated with multiple cellular processes, such as cell differentiation, proliferation, apoptosis, especially during cancer progression." (PMID 26177288, 2015). "In addition, abnormal Sp1 levels are highly correlated with stage and poor prognosis of cancer." (PMID 25816367, 2015). "Some Sp1-driven transcriptional induction mechanisms that are not necessarily associated with hypoxia or cancer cells will also be discussed in relation to their potential involvement in the adaptation of cancer cells to an oxygen-deficient tumor microenvironment." (PMID 26703734, 2015). "Our results demonstrate Sp1 could serve as an efficient therapeutic target of cancer." (PMID 24423061, 2014). "Furthermore, down-regulation of Sp1 may suppress the acquisition of cancer stem cell phenotypes through the reduced expressions of SCTFs, including Bmi1, c-Myc and KLF4." (PMID 25099028, 2014). "Therefore, the cancer-promoting role of Sp1 may also be mediated by transcriptional activation of its downstream genes, such as Bmi1 and CENPH." (PMID 25099028, 2014). "Therefore, the downregulation of Sp1 by naturally occurring compounds may be a potential chemopreventive and chemotherapeutic strategy for cancer." (PMID 23403540, 2013). "SP1 is an essential transcription factor for many genes whose abnormal function may result in tumor cell development, differentiation, and proliferation in various types of cancers, including breast and pancreatic." (PMID 23437057, 2013). "In addition, sub-cytotoxic MJ decreased the specificity protein 1 (Sp1) expression and binding on MMP-14 promoter, while restoration of Sp1 expression rescued the cancer cells from sub-cytotoxic MJ-mediated defects in MMP-14 expression, migration, invasion and angiogenesis." (PMID 23394613, 2013). "Therefore, it is likely that Sp1 is an important target for cancer therapy." (PMID 23403540, 2013). "Moreover, as the tumor advanced to carcinoma, high SP1 expression was frequently observed (72.8%)." (PMID 23437057, 2013). "In addition, recent studies have investigated several compounds with anti-cancer activity that could inhibit Sp1 transcriptional activity." (PMID 23148884, 2012). "Both miR-375 and its target genes, 14-3-3zeta and SP1, might be therapeutic targets, and either restoring miR-375 expression or abolishing expression of 14-3-3zeta and SP1 genes could diminish malignant cell behaviors and consequently block the progression of cancer." (PMID 22606351, 2012). "Sp1 could contribute to cell growth via numerous gene expression regulation in various cancers." (PMID 22734486, 2012). "It is therefore reasonable to hypothesize that downregulation of miR-375 results in enhanced expression of 14-3-3zeta and SP1 and provides a survival advantage for cancer cells, in contrast, upregulation of miR-375 diminishes the expression of 14-3-3zeta and SP1 and leads to cellular senescence." (PMID 22606351, 2012).
cancer (continued). "Furthermore, abnormal Sp1 protein levels have been correlated with cancer stage and poor prognosis." (PMID 23028678, 2012). "Moreover, several anticancer agents including NSAIDs and GT-094 (a NO-NSAID), curcumin, betulinic acid and synthetic triterpenoids, and arsenic trioxide decrease expression of Sp1, Sp3, Sp4 and Sp-regulated genes in cancer cells and these effects contribute to their anticancer activity." (PMID 23110215, 2012). "Collectively, our results demonstrate the important roles that Sp1 and NF-κB play in regulating the expression of the human telomere-binding protein TIN2, which can shed important light on its possible role in causing various forms of human diseases and cancers." (PMID 21731707, 2011). "Therefore, investigation of the relationship between κB4 and Sp1 might provide evidence for using κB4 to improve the transcriptional activity of other cancer-specific promoters." (PMID 17687334, 2007). "Ligands activated RARα/Sp1-induced monoamine oxidase B (MAO-B), CADM1, E-cadherin and the folate receptor-β gene (FRβ) in cancer cells." (PMID 39858066, 2025). "Hyperactivation of both YAP/TEAD and SP1 is commonly observed in human cancers, and multiple transcription factors have been reported to cooperate with YAP/TEAD or SP1 to drive tumorigenesis and tumor progression." (PMID 39875519, 2025). "As an important pro‐cancer transcription factor, we used JASPAR to predict and verify the transcriptional activity of SP1 in activating TGF‐β, which revealed the important role of the VIRMA‐SP1‐TGF‐β axis in CRLM." (PMID 41017455, 2025). "These intriguing findings shed light on the complex and context-dependent roles of SP1 and KLF5 in cancer metastasis." (PMID 39748426, 2025). "Other examples of GR/Sp1 (NR3C1/Sp1) mineralocorticoid receptor/Sp1 and ERR/Sp were also observed in a non-cancer cell context." (PMID 39858066, 2025). "Other sub-group II receptors: Among the remaining NRs in this subgroup, testicular receptor 4 (TR4) is the receptor that activates genes (e.g., apoE) in cancer cells, and this involves both TR4 response elements alone and in combination with Sp1." (PMID 39858066, 2025). "Additionally, TRF2 may assist tumor cells in evading immune surveillance, since inhibition of TRF2 has been shown to promote the activation of NK cells.From the perspective of telomere biology, NEK7 and SP1 may also emerge as potential targets for future cancer therapies." (PMID 39871386, 2025). "Through functional perturbation, we identified SP1 and KLF5 as crucial regulators, acting as drivers and suppressors of metastasis, respectively, across multiple cancer types." (PMID 39748426, 2025). "SP1 acts as a driver of metastasis, while KLF5 functions as a suppressor across multiple cancer types at defined time points of the metastatic transition." (PMID 39748426, 2025). "We were particularly interested in two TFs, SP1 and KLF5, given their previous implications in cancer metastasis and opposite kinetics in our data during metastasis progression." (PMID 39748426, 2025). "In cancer cells, RARα/RXRα (NR1B1/NR2B1) interacts with Sp1 and Sp3 on the 17β-hydroxysteroid dehydrogenase type 2 (HSD17B2) promoter, and retinoic acid (RA) induces its expression." (PMID 39858066, 2025). "In summary, CENP-H is involved in cancer growth and metastasis through PI3K/AKT, survivin, and mitochondrial apoptosis signaling mechanisms and can be regulated by lncRNA PVT1/miR-612, Sp1, or Sp3." (PMID 40071086, 2025). "Sp1 target genes participate in cell proliferation and oncogenesis in many cancers, notably CRC, as their responsive genes are hallmarks of cancer." (PMID 40869407, 2025). "Therefore, the Sp1 protein could be considered one of the protective factors in cancer." (PMID 40723802, 2025).
cancer (continued). "CENP-H can promote cancer growth and metastasis through PI3K/AKT, Survivin, and mitochondrial apoptosis signaling mechanisms, and it can be regulated by lncRNA PVT1/miR-612, Sp1, or Sp3." (PMID 40071086, 2025). "PPARα agonists also decreased the PPARα/Sp1-dependent expression of KDR and Cyp7b1 and induced pl6NK4a in non-cancer cell lines." (PMID 39858066, 2025). "Although it has been reported that SP1 and NFYA are transcription factors that regulate the transcription activity of Snd1 in cancer cells, in this study, we demonstrated that both of them did not affect Snd1 transcription activity in VSMCs." (PMID 38279051, 2024). "On the contrary, mir-21 induces the expression of SP1, MYC, and HIF1A and promotes cancer progression via the induction of immune-suppressive mechanisms." (PMID 39590335, 2024). "In hepatocellular carcinoma cells, TERT binding to Sp1 stimulates DNMT3B transcription and induces aberrant cancer-specific global DNA methylation and AKT hyperactivation." (PMID 38278800, 2024). "The transcription factor SP1 promotes the expression of CYTOR, which, in turn, promotes the metastasis of cancer cells through the PI3K/AKT pathway." (PMID 39058104, 2024). "Meanwhile, it was shown by several systems analyses that SP1, HIF1A, and MYC functioned as master regulators of cancer development." (PMID 39590335, 2024). "YM155 is the first discovered small molecule survivin inhibitor, and it can significantly downregulate survivin expression by disrupting the survivin transcription factor Sp1, ILF3, and p54nrb in cancer cells 54-56." (PMID 38356707, 2024). "So far, we have presented several pieces of evidence to support the concept that SP1, HIF1A, and MYC collaborate to promote cancer development and that inhibitors of these transcription factors should induce strong anticancer activity." (PMID 39590335, 2024). "Overexpression of the transcription factors Specificity protein 1 (Sp1) and Specificity protein 3 (Sp3) independently increases PDPN transcription in certain cancer cell lines." (PMID 39682237, 2024). "c-FLIP has been identified as a key negative regulator of apoptosis in human cancer cells, and its expression is controlled by several transcription factors, including AP-1 (c-Fos and c-Jun), CREB, SP1, and NF-kB." (PMID 39395071, 2024). "For example, in the DLX4 gene module, connections among DLX4, the known cancer gene ABL1, and four candidate AML genes (SP1, FYN, GRB2, and SMAD2) co-occurred in multiple patients." (PMID 39013885, 2024). "Clearly, further work will be essential to unravel precise pathways contributing to SP1 activation potentially beyond ERK1/2 and the differences in the SP1 transcriptomes in HPV16+ and HPV18+ cancers." (PMID 38987584, 2024). "TIMER database was used for pan‐cancer analysis of different pain genes (Nav1, EHMT2, SP1, SLC6A4, COMT, OPRM1, OPRD1, CYP2D6, and CYP3A4)." (PMID 38352696, 2024). "Multiple Sp1 PTMs, such as phosphorylation and ubiquitination, phosphorylation and acetylation, SUMO, and ubiquitination, can co-regulate a particular cancer type." (PMID 39228402, 2024). "Mechanistically, Sp1, the transcription factor of VEGF, interacts with TERT and facilitates angiogenesis in cancer via VEGF activation." (PMID 38278800, 2024). "Among the transcription factors, SP1 was the only regulator that was common in both LPL and PCK1, and it mainly plays a role in transcriptional mis-regulation in cancer." (PMID 38791477, 2024). "To examine the gene expression of AP1G1 and SP1, we first used the TIMER database to analyze the levels of AP1G1 and SP1 in different cancers." (PMID 39056681, 2024). "M4N is a dual inhibitor of SP1 and HIF1A but only occasionally works as a MYC inhibitor for certain cancer cells specifically." (PMID 39590335, 2024). "Our concept and the data presented here indicated that SP1, MYC, and HIF1A were the missing links between miRNAs and cancer stem cells." (PMID 39590335, 2024).
cancer (continued). "Therefore, Sp1 degradation mediated by increased ubiquitination may inhibit cancer." (PMID 39228402, 2024). "Some studies have accounted for predicted and validated gene targets like GATA2, SKI, NTRK3, PAK2, AR, SP1, and CDK4 that describe their involvement in cancer progression." (PMID 38741808, 2024). "Both SP1 and HIF-1 are also involved in the regulation of cellular stress mechanisms as mediators of the protection of cancer cells against various stresses." (PMID 37998757, 2023). "Nevertheless, all of the inhibitors against SP1, HIF1A, or MYC can be considered potential anticancer drugs due to the nature of these TFs as master regulators of cancer." (PMID 37998757, 2023). "First, as described in Section 2, all HIF-1, SP1, and MYC are deeply involved in cancer-related cellular mechanisms including metabolism, angiogenesis, anticancer immunity, and regulation of TME." (PMID 37998757, 2023). "By knocking down these four candidate transcriptional factors using siRNA in cultured ccRCC cancer cells, we found the mRNA levels of G6PD and PGD decreased in SP1 knocking down cells." (PMID 37460463, 2023). "In this review, we provide an overview of the interactions and collaborations of SP1, HIF1A, and MYC in the regulation of various cancer-related genes, and their potential implications in the development of anticancer therapy." (PMID 37998757, 2023). "This loop promotes the acquisition of cancer stem-like properties and impedes the antitumor efficacy of gemcitabine in PAAD by activating the CCL5/CCR5/Sp1/CD44 axis." (PMID 37553567, 2023). "SP1, HIF-1, and MYC are three major TFs that play important roles as master regulators of cancer, so the next question is—what are these TFs and how do they benefit cancer as regulators of gene expression?" (PMID 37998757, 2023). "Because each compound showed different SP1 element binding specificities, treating MPM cancer cells with a defined EPE mixture seems more reasonable." (PMID 37894370, 2023). "To investigate its potential for cancer treatment in PAAD, we used siRNA and shRNA technology to silence Sp1." (PMID 37553567, 2023). "In the Myc datasets (GSE22139, GSE11791), multiple top-ranked TFs, such as MAX, SP1, NRF1, and E2F4, are known to interact with MYC in regulating the expression of common target genes in cancer cells." (PMID 38032891, 2023). "SP1, HIF-1, and MYC are often overexpressed in tumors, which indicates the importance of their roles in the development of cancer." (PMID 37998757, 2023). "For instance, both SP1 and HIF-1 play important roles in the regulation of cancer metabolism in carbohydrates and lipids." (PMID 37998757, 2023). "This indicates that HIF-1 and SP1 can cooperatively activate cancer-related cellular mechanisms while the relationship between HIF-1 and MYC regarding the regulation of cancer-related cellular mechanisms can be variable depending on the context." (PMID 37998757, 2023). "SP1 and MYC are well-known cancer regulators, which have been reported to be highly expressed in diseased tissues." (PMID 36212136, 2022). "Transcription factors, including Sp1, AP-2, BRCA, E2F1 and MYBL2, bind to the DNA sequence in the promoter region of RRM2 and regulate their expression in response to DNA damage in cancer cells." (PMID 35651787, 2022). "Ectopic overexpression of Sp1 led to resistance against betulinic acid in PANC-1 and BxPC-3 cancer cells." (PMID 36615262, 2022). "Previously, we reported that Sp1 promotes the development of malignant characteristics in GBM, including drug resistance and cancer stem cell enrichment." (PMID 35337344, 2022). "lncRNAs HOTAIR, SP1, and PDK1 exhibit oncogenic effects in many tumors and are involved in cancer development and progression by mediating multiple signaling pathways." (PMID 36313365, 2022). "This subclass is characterized by Wnt activation, cyclic AMP driven transcription, and SP1 activation, and emerges in fibroblasts at stage IIB as the cancer trespasses the stroma." (PMID 35565326, 2022).
cancer (continued). "In summary, our results show the relevance of SP1 and NFY in PNPT1 expression, and point to SP1/NFY and PNPase as possible targets in anti-cancer therapy." (PMID 36232701, 2022). "Many studies have shown that SP1 promotes the transcriptional activation of genes and that SP1 and COL1A1 are highly expressed in a variety of cancers, suggesting that SP1 and COL1A1 are positively correlated." (PMID 36360208, 2022). "Specificity protein 1 (SP1), an essential transcription factor in many cancer cells, has also been shown to regulate FHL2 expression by binding upstream of the FHL2 transcription start site." (PMID 34685595, 2021). "The transcription factor specificity protein 1 (SP1) and Yes-associated protein (YAP) can individually interact with β-catenin and both SP1 and YAP are part of the destruction complex to regulate the β-catenin stability in cancer cells." (PMID 32814878, 2021). "The upstream of MALAT1 contains 5 specific protein 1/3(SP1/3) binding sites, and the combined regulation of SP1 and SP3 in cancer cells promote the expression of MALAT1." (PMID 35145971, 2021). "According to the results, MGST1, GPX3, SP1, TXNRD1, MAPK14, and SOD1 presented with CNV gains among various types of cancers." (PMID 34721758, 2021). "Our results showed that miR-27a suppressed ZBTB10 in cancer cells and antisense miR-27a induced ZBTB10 expression with downregulation of Sp1, Sp3, Sp4 and pro-oncogenic Sp-regulated genes." (PMID 34072678, 2021). "SP1 expression is connected with lymph node metastasis, TNM stage and infiltration depth, suggesting it can be considered as a potential target for cancer treatment in the future." (PMID 34257529, 2021). "Specificity protein 1 (SP1) is a transcription factor involved in the apoptosis, proliferation, and differentiation of cancer cells." (PMID 34494089, 2021). "Taken together, our data indicate that GABPA and Sp1 synergistically activate mutant TERT promoter, contributing to tumorigenesis and cancer progression, particularly in the BRAFV600E-driven human cancers." (PMID 33483600, 2021). "Four of these (Sp1, NBL1, MINOS1-NBL1, and MAPK1) were predicted to be target genes of miR-2110; hence, we selected miR-2110 according to its probable cancer-related downstream pathway." (PMID 34145213, 2021). "This Sp1 expression in turn induces the production of CCL1 in activated LECs to recruit TAMs and cancer cells, resulting in lymphatic vessels encapsulated by TAMs (LVEM) to promote cancer metastasis." (PMID 36046433, 2021). "Previous studies suggest that SP1 activates Glut1 and PKM2 via binding motifs in promoters in cancers." (PMID 32158359, 2020). "For example, acetylated SP1 was reported to be able to suppress PTEN expression via binding to PTEN promoter and recruitment of HDAC1 and promote cancer cell migration and invasion." (PMID 32432112, 2020). "It has been demonstrated that ZEB2 interacts with the transcription factor Sp1 to activate the expression of mesenchymal genes and vimentin expression, leading to EMT in human cancer cells." (PMID 32149094, 2020). "c-Myc directly associates with the MH2 domain of SMAD2 and SMAD3 to inhibit the TGF-β-induced transcriptional activity of Sp1 and SMAD/Sp1-dependent transcriptions of the p15Ink4B gene and eventually promotes cell growth and cancer progression." (PMID 32340410, 2020). "The Sphingosine-1-Phosphate Transporter (SP1) gene MFSD2B, a regulator of self-renewal and differentiation in neural and cancer progenitor cells, was also differentially methylated at multiple CpG sites (n = 6)." (PMID 32046773, 2020). "A growing evidence indicate that downregulation of Sp1 and Sp3 expressions by drugs or RNA interference can induce autophagy by depressing EGFR activity and downstream the AKT/MAPK pathways in cancer cells 20,36." (PMID 32226300, 2020).